CXCL16 (C-X-C motif chemokine ligand 16)
Diseases named in the same sentence as CXCL16 in open-access papers (continued):
Sharing a sentence is not in itself a finding about the gene and the disease.
asthma (continued). "According to literature reports, CXCL16 is expressed in macrophages, peripheral lymphocytes, dendritic cells, and epithelial cells, and CXCL16 was discovered in bronchoalveolar lavage fluid, indicating that CXCL16 on inflammatory cells plays a vital role in asthma development." (PMID 40050290, 2025). "CXCL6 and CXCL16 were particularly noteworthy because of their increased concentrations in NPAs from hRSV-positive children and their association with several chronic lung pathologies, such as idiopathic pulmonary fibrosis (IPF), CF, chronic rhinosinusitis (CRS) and asthma." (PMID 32075873, 2020). "CXCL16 knockout in DCs inhibits antigen processing and presentation by suppressing the expression of the MHC class II molecule H2-DM, suggesting that inhibition of CXCL16 can be a potential therapy for asthma." (PMID 40050290, 2025). "Adoptive transfer experiments further confirmed that the DCs expressed CXCL16, but no other type of cells expressed CXCL16 exhibited a promoting role in asthma airway inflammation." (PMID 40050290, 2025).
breast tumors (6 papers, 2016 to 2023). "It is important to highlight that the CXCL16 expression by fibroblasts was found to vary among TN breast tumors." (PMID 36358879, 2022). "IHC of CXCL16 on primary breast tumours revealed that both ER+ and TN tumour cells expressed CXCL16 (black arrow), and that fibroblasts in the TN tumour also expressed CXCL16 (red arrow)." (PMID 27725631, 2016). "In light of this, we suggest that CXCL16 may be viewed as a monocyte and fibroblast chemoattractant expressed in human breast tumours." (PMID 27725631, 2016). "When compared against stromal cells derived from primary breast tumors or healthy breast tissue, they found that the stromal cells that had lodged themselves in the brain expressed the highest levels of CXCL12 and CXCL16, two chemokines involved in cell movement." (PMID 28649646, 2017). "Since CXCL16 can attract T cells, NKT cells, myeloid cells and also fibroblast precursors, these findings are of large importance when it comes to understanding why the tumour stroma in TN breast tumours in particular, attracts immune cells." (PMID 27725631, 2016).
chronic kidney disease (6 papers, 2012 to 2022). Impairment of the renal function secondary to chronic kidney damage persisting for three or more months. "Also, serum levels of CXCL16 were increased in the case of gout, in addition to chronic kidney diseases (CKD), and is accompanied by deterioration of renal function." (PMID 35335970, 2022). "Thus our findings suggest that CXCL16/CXCR6 pathway may contribute to progression of end-stage renal diseases." (PMID 33922243, 2021).
heart failure (6 papers, 2016 to 2025). Inability of the heart to pump blood at an adequate rate to meet tissue metabolic requirements. "More importantly, CXCL16 plays an important role in the progression of heart failure through controlling the matrix remodeling." (PMID 33637127, 2021). "In 174 patients with heart failure, myocardial biopsy samples stained for CXCL16 showed significantly enhanced expression in inflammatory cardiomyopathy compared with non-inflammatory cardiomyopathy." (PMID 33182772, 2020). "CXCL16 has also been proposed as a prognostic biomarker in inflammatory cardiomyopathy and heart failure." (PMID 33182772, 2020). "In addition, CX3CL1, an atypical chemokine that, like CXCL16, exists in both membrane-bound and soluble forms, is also detected in hearts and serum of patients with heart failure." (PMID 27525724, 2016). "Soluble CXCL16 in the serum, when bound to CXCR6, plays an important role in pathological mechanisms following I/R injury in cardiac remodeling and heart failure development." (PMID 40535169, 2025). "CXCR6 is the specific receptor for CXCL16, and the CXCL16/CXCR6 axis plays an important role in pathological mechanisms following I/R injury in cardiac remodeling and heart failure development." (PMID 40535169, 2025). "Proteolytically derived soluble fragments or splice isoforms of CD36, LOX-1, CXCL16, and RAGE are potential biomarkers for a range of CVD conditions, including ACS, cardiac failure, cardiomyopathy, and carotid artery disease." (PMID 33182772, 2020). "Similarly, CXCL16 is found at high levels in the plasma of patients with right-ventricular hypertrophy due to pulmonary stenosis and those with LVH in heart failure; in the latter case, expression levels correlated with disease severity." (PMID 27525724, 2016).
non-small cell lung carcinoma (6 papers, 2015 to 2021). A group of at least three distinct histological types of lung cancer, including non-small cell squamous cell carcinoma, adenocarcinoma, and large cell carcinoma. "One source of CXCL16 in tumors are CAFs, as shown in triple-negative breast cancers and non-small cell lung cancer." (PMID 33800554, 2021). "Here, we present evidence that chemokine receptor CXCR6 and its only natural ligand, CXCL16, are significantly expressed by non-small cell lung cancer (NSCLC) and are involved in the pathobiology of LuCa." (PMID 25888629, 2015). "The expression of CXCR6 and CXCL16 has been examined in numerous human cancers; however no studies have yet investigated their influence on prognosis in non-small cell lung cancer (NSCLC)." (PMID 26021984, 2015).
pulmonary fibrosis (6 papers, 2019 to 2024). Chronic progressive interstitial lung disorder characterized by the replacement of the lung tissue by connective tissue, leading to progressive dyspnea, respiratory failure, or right heart failure. "In summary, our research revealed the increased secreation of CXCL16 from M2 macrophages in the context of bleomycin-induced pulmonary fibrosis, which was associated with the recruitment of CXCR6+ CD4 T cells." (PMID 38789926, 2024). "Chemokines, such as CXCL12, CCL1, and CCL18, are implicated in pulmonary fibrosis, acting as chemoattractants by combining with the chemokine receptors, and yet the role of CXCL16 and its receptor remain poorly understood." (PMID 38789926, 2024). "Our data indicate the therapeutic effect of bortezomib in the mouse model of pulmonary fibrosis, which is associated with reduced CXCL16 secretion." (PMID 38789926, 2024). "It was also determined that CXCL16/CXCR6 contributed to pulmonary fibrosis in RA-ILD patients by up-regulating proliferation and collagen accumulation of human pulmonary fibroblasts (MRC-5 cells) mediated by the PI3K/AKT/FOXO3a pathway." (PMID 37833957, 2023). "Further research is necessary to assess the role of CXCL16 in pulmonary fibrosis and its potential as a therapeutic target in fibrosis-related diseases." (PMID 33549109, 2021). "In this study, the potential role of CXCL16 in regulating EMT in BLM-induced pulmonary fibrosis in human A549 cells was investigated." (PMID 33549109, 2021). "It was determined that the serum level of sCXCL16 was significantly increased in RA-ILD patients, and CXCL16/CXCR6 could contribute to the severity of pulmonary fibrosis." (PMID 37833957, 2023). "However, the detailed biological function of CXCL16 is still not fully understood in the progression of pulmonary fibrosis (PF)." (PMID 31379980, 2019). "Pro-inflammatory and pro-fibrotic cytokines forms a complex regulation network during the occurrence and development of pulmonary fibrosis, whether CXCL16 modulate BLM-induced pulmonary fibrosis via promoting secretion of the pro-inflammatory and pro-fibrotic cytokines is still unknown." (PMID 33549109, 2021). "Here, we observed that the expression of CXCL16 and CXCR6 was elevated in the lung tissue of a pulmonary fibrosis model." (PMID 38789926, 2024). "Up-regulation of CXCL16 and CXCR6 in bleomycin-induced EMT in human alveolar type II epithelial cells promotes pulmonary fibrosis via the TGF-β1/Smad3-signaling pathway." (PMID 39768150, 2024). "In the context of pulmonary fibrosis or TGF-β1 stimulation in vitro, macrophages exhibited an M2-polarized phenotype and secreted more CXCL16 than those of the control group." (PMID 38789926, 2024). "Serum CXCL16 levels are higher in RA-ILD patients, correlating with lung fibrosis severity." (PMID 39768150, 2024). "To decipher the immune milieu in pulmonary fibrosis, we first analyzed the GEO dataset (GSE213709) and observed upregulation of the chemokine signaling pathway along with markedly increased mRNA expression of CXCL16 in the pulmonary fibrosis model." (PMID 38789926, 2024). "We further verified the synergistic effect of CXCL16 and BLM in the process of pulmonary fibrosis." (PMID 33549109, 2021). "However, little is known whether CXCL16 is dysregulated in alveolar epithelial cells and the role of CXCL16 in modulating EMT in pulmonary fibrosis." (PMID 33549109, 2021). "However, whether CXCL16 is dysregulated in alveolar epithelial cells and the role of CXCL16 in modulating EMT in pulmonary fibrosis has not been reported." (PMID 33549109, 2021). "However, whether CXCL16 is also dysregulated in the human alveolar epithelial cells and the role of CXCL16 in modulating EMT in pulmonary fibrosis has not been reported." (PMID 33549109, 2021).
type 2 diabetes (6 papers, 2012 to 2024). "In a case-control study in patients with type 2 diabetes, elevated plasma levels of chemokine ligand-16 (CXCL-16), angiopoietin-2, and TGF-β1, which are systemic biomarkers of inflammation, fibrosis and endothelial dysfunction, are independently associated with the development of microalbuminuria." (PMID 38542060, 2024). "Metformin, a first-line agent for type 2 diabetes treatment, was demonstrated to reduce the gene expression levels of several fibrotic markers, including α-SMA, Collagen1α1, and TGF-β1, which is associated with the reduction of CXCL16 mRNA expression." (PMID 36636609, 2023).
viral infection (6 papers, 2010 to 2023). "Although RABV infection seems not to result in excitotoxicity in vitro, CXCL16 might modulate neurotransmission during viral infection." (PMID 34804996, 2021). "Then in vitro assays verified that virus infection, simulated by Poly(I:C), could promote the secretion of CXCL10 and CXCL16." (PMID 32532953, 2020). "Combined with our previous finding that NF-κB P65 could directly mediate the transcription of CXCL16 in keratinocytes through directly binding to the promotor of CXCL1645, we draw a conclusion that CXCL16 is mainly elaborated by IRF3 and NF-κB in the downstream of MAVS under virus infection." (PMID 32532953, 2020).
autoimmune disease (5 papers, 2009 to 2025). A disorder resulting from loss of function or tissue destruction of an organ or multiple organs, arising from humoral or cellular immune responses of the individual to their own tissue constituents. "In immune cell adhesion, CXCL16 facilitates the attachment of immune cells to endothelial and dendritic cells, contributing to the pathogenesis of multiple autoimmune diseases." (PMID 41357074, 2025). "Therefore, the CXCL16/CXCR6 axis may be a potential therapeutic target for tumors, kidney diseases, cardiovascular diseases, non-alcoholic fatty liver disease 43, and autoimmune diseases." (PMID 40722833, 2025).
cervical cancer (5 papers, 2021 to 2025). A primary or metastatic malignant neoplasm involving the cervix. "Meanwhile, according to MCC scores from the CytoHubba plugin in Cytoscape, the top 5 cervical cancer-related genes were screened out (MEF2C, CXCL16, IRF4, OAS3, PTGER3)." (PMID 34020619, 2021). "A new cytokine (CXCL16) was investigated together with the chemokine receptor combination CXCL12/CXCR4 and CXCL16/CXCR6 in cervical intraepithelial neoplasia (CIN) and cervical cancer." (PMID 34833360, 2021). "Moreover, the CXCL16/CXCR6 complex may be useful as a biomarker and a valuable prognostic factor for cervical cancer." (PMID 34833360, 2021).
colitis (5 papers, 2013 to 2022). Inflammation of the colon. "Cxcl16 was critical for the accumulation of invariant natural killer cells into the tissues and for sensitization to oxazolone induced colitis." (PMID 23977377, 2013). "In germ free mice increased numbers of CXCR6+ iNKT cells are found in colon and lung due to increased CXCL16 expression and both colitis and lung allergic responses are increased." (PMID 23262169, 2013). "Furthermore, administration of an anti-CXCL16 mAb ameliorates inflammation in a chemically induced experimental colitis model." (PMID 23840334, 2013). "Similarly, colitogenic invariant natural killer (iNKT) cells also accumulate in colonic LP in a CXCL16-dependent manner and increase morbidity in oxazolone-induced experimental colitis under germ-free conditions." (PMID 23840334, 2013). "Recently, the expression of CXCL16, a CXC family chemokine, has been reported to be upregulated in the colon of CD patients and in mouse models of colitis." (PMID 23840334, 2013).
nasopharyngeal carcinoma (5 papers, 2009 to 2025). A carcinoma arising from the nasopharyngeal epithelium. "The high expression of CXCR6 on LCL-derived VST is consistent with a previous study where CXCL16 secretion from nasopharyngeal carcinoma recruited CXCR6high T cells to the tumor site." (PMID 39011042, 2024).
pancreatic ductal adenocarcinoma (5 papers, 2020 to 2024). An infiltrating adenocarcinoma that arises from the epithelial cells of the pancreas. "NF-κB can affect the infiltration of CD8+ T-cells in pancreatic ductal adenocarcinoma cells by regulating the generation of CXCL16 and CX3CL1 and thereby promoting the apoptosis of pancreatic ductal adenocarcinoma cells." (PMID 33062724, 2020).
prostate tumor (5 papers, 2014 to 2022). "It is now known that CXCL16 secreted by prostate tumor cells are capable of recruiting mesenchymal stem cells to TME and promoting their transition to become CAFs." (PMID 32585812, 2020). "In addition, one of the most serious complications of prostate tumours is skeletal metastases, and the CXCL16/CXCR6 axis functions in chemoattraction to induce metastasis." (PMID 35869057, 2022). "CXCL16 signalling can be induced by IFN-γ, TNF-α and IL-1β, which are involved in the migration and invasion of prostate tumour cells." (PMID 35869057, 2022). "Prostate tumour cells show a high metastatic capacity, and metastasis to secondary sites (such as skeletal tissues) can be enhanced by MSC stimulation via CXCL16/CXCR6 signals." (PMID 35869057, 2022). "In prostate tumours, inhibiting CXCR-6 expression can interrupt the differentiation of MSCs into CAFs and decrease the CXCL-12 secretion of CAFs via Erk and NF-κB signalling, and knockdown of CXCL16 in vitro also inhibits the formation of CAFs." (PMID 35869057, 2022).
sarcoidosis (5 papers, 2009 to 2017). Sarcoidosis is a multisystemic disorder of unknown cause characterized by the formation of immune granulomas in involved organs. "High levels of CXCL16 are found in the lung of patients with sarcoidosis, or interstitial lung diseases." (PMID 28267793, 2017). "In contrast to our negative findings regarding macrophage polarization, previous studies have demonstrated higher expression of the M1 markers CXCL10, CXCL11 and CXCL16 in sarcoidosis patients compared to healthy subjects." (PMID 20813038, 2010).
systemic lupus erythematosus (5 papers, 2014 to 2025). An autoimmune multi-organ disease typically associated with vasculopathy and autoantibody production. "The results demonstrated a significant upregulation and enrichment of CXCL16 in Viral protein interaction with cytokine and cytokine receptor, Systemic lupus erythematosus, Renin−angiotensin system and Pertussis." (PMID 38979407, 2024).
thyroid cancer (5 papers, 2018 to 2022). "CXCL16 expression in thyroid cancer cells is associated with high expression of M2 polarization markers and pro-angiogenic markers, and positively correlates with poor prognosis in human papillary thyroid cancer." (PMID 34209679, 2021). "In the present study, we first reported that targeting CXCL16 either in cancer cells using shRNA or in the microenvironment using a neutralizing antibody efficiently blocked tumor growth and angiogenesis in thyroid cancers." (PMID 31527616, 2019). "At present, CCL2, CCL15, CCL20, CXCL1, CXCL8, CXCL12, and CXCL16 are the main chemokines showing a role in thyroid cancer." (PMID 29977225, 2018). "A three-gene panel related to CXCL16 can be used to predict the disease prognosis, and targeting CXCL16 may be a good therapeutic strategy for macrophage-enriched, advanced thyroid cancer." (PMID 31527616, 2019). "Taken together, a 3-gene panel that includes CXCL16 can predict a poor prognosis for PTCs, and targeting CXCL16 may be a good therapeutic strategy for advanced thyroid cancers." (PMID 31527616, 2019). "Collectively, the inhibitions of CXCL16 by targeting either the tumor cells or tumor microenvironment could be an effective therapeutic strategy for advanced thyroid cancer." (PMID 31527616, 2019). "Moreover, miR-873-5p could regulate chemokine (C-X-C motif) ligand 16 (CXCL16) expression to inhibit thyroid cancer progression." (PMID 34497766, 2021). "Targeting CXCL16 may be a good therapeutic strategy for advanced thyroid cancer." (PMID 31527616, 2019). "Therefore, CXCL16 can be another target for anti-angiogenic therapy in advanced thyroid cancer, and patients with higher CXCL16 expression might be selected for challenge targeting CXCL16 as a precision medicine approach." (PMID 31527616, 2019). "On the other hand, CXCL16 was reported to positively correlate with M2-TAM infiltration, increased angiogenesis, and worse prognosis in thyroid cancer." (PMID 35366939, 2022). "The authors suggested that depletion of CXCL16 in cancer cells and other cells of the TME can be an effective therapeutic strategy for advanced thyroid cancer." (PMID 34209679, 2021). "First, shCXCL16 was transduced into two thyroid cancer cell lines, BHP10-3SCp and FRO, resulting in the genetic depletion of endogenous CXCL16." (PMID 31527616, 2019). "Studies taking into account the role of CCL15, C–X–C motif ligand 12, CXCL16, CXCL1, CCL20, and CCL2 in the context of thyroid cancer will be reviewed with particular emphasis on CXCL8." (PMID 29977225, 2018).
brain tumor (4 papers, 2016 to 2022). "Since CXCL16 was able to activate Akt via inverse signaling mechanisms in brain tumors, the PI3K-AKT signaling pathway might be involved in the regulation of VEGFC expression via CXCL16, and probably via CX3CL1, during cellular dormancy exit." (PMID 32346064, 2020).
Cognitive impairment (4 papers, 2023 to 2025). Abnormal cognition is characterized by deficits in thinking, reasoning, or remembering. "Two studies reported significantly different concentrations of markers in individuals with MCI: CXCL11, CCL13, and CCL15 were increased, and CXCL16 and IL-16 were decreased in individuals with mild cognitive impairment compared to controls." (PMID 40711681, 2025). "Peripheral blood mRNA expression of CXCL16 was upregulated in mild cognitive impairment (MCI) and AD patients, indicating the potential of CXCL16 as a biomarker for AD development." (PMID 36670424, 2023).